AR (androgen receptor)
Diseases named in the same sentence as AR in open-access papers (continued):
Sharing a sentence is not in itself a finding about the gene and the disease.
bladder cancer (continued). "However, the signaling involvement of GRβ and AR in bladder cancer has not been investigated." (PMID 27036026, 2016). "Furthermore, BBN completely failed to induce bladder cancer in AR knockout mice." (PMID 26770009, 2015). "We therefore investigated whether ELK1 could affect the viability and migration of AR-positive bladder cancer cells in the absence of androgens and whether androgen could enhance the viability and migration of AR-positive ELK1-shRNA-expressing bladder cancer cells." (PMID 26342199, 2015). "Thus, in contrast to its function in cell proliferation, ELK1 may not require activated AR to regulate bladder cancer cell migration." (PMID 26342199, 2015). "On the other hand, in bladder cancer cells, cell proliferation can be induced by DHT stimulation, even in the absence of AR expression, suggesting that the AR is not the only receptor responsible for this effect." (PMID 37681860, 2023). "In a study using AR knockout (ARKO) mice, BBN completely failed to induce bladder cancer by 40 weeks." (PMID 32759680, 2020). "Thus, AR expression may not necessarily serve as a prognosticator in patients with bladder cancer." (PMID 28241422, 2017). "In contrast to our current findings, in a study where the effects of androgen treatment and AR silencing on cytotoxicity of doxorubicin, 5-fluorouracil, and CDDP in bladder cancer cells were examined, androgen failed to modulate sensitivity to CDDP." (PMID 27322140, 2016). "DHT increased ELK1 gene expression in two AR-positive bladder cancer sublines, UMUC3-control-shRNA (3.4-fold) and 647V-AR (3.2-fold), but not in AR-negative sublines." (PMID 26342199, 2015). "We then performed the MTT assay to investigate the effects of EGF androgen and antiandrogen on cell proliferation of bladder cancer lines with vs. without AR (i.e., UMUC3-control-shRNA vs. UMUC3-AR-shRNA, 5637-AR vs. 5637-V and J82-AR vs. J82-V)." (PMID 22922989, 2012). "Bladder cancer cell lines responded to DHT treatment with increased proliferation, regardless of androgen receptor expression levels." (PMID 18433501, 2008). "Moreover, in bladder cancer lines, DHT and silodosin did not significantly induce and inhibit the proliferation of ELK1 knockdown cells and that of AR-negative cells or AR-positive cells cultured in an androgen-depleted condition, respectively." (PMID 32759680, 2020).
breast tumors (130 papers, 1996 to 2026). "DNA copy number analysis was performed to determine the impact of the loss of AR expression on genomic instability in breast tumors." (PMID 34768979, 2021). "To examine the association between circulating testosterone and AR expression in breast tumors, we estimated the total serum testosterone levels in patients at first diagnosis by chemiluminescence method." (PMID 34234742, 2021). "Drugs that block the androgen receptor (AR) protein can help make radiation-resistant breast tumors susceptible to ionizing therapy." (PMID 28840192, 2017). "Increased AR expression is found in tamoxifen-resistant breast tumors and overexpression of AR in MCF-7 cells caused the cells to become resistant to growth inhibition by tamoxifen." (PMID 24534923, 2014). "The combined HR of DFS for all 12 eligible studies was 0.52 (95% CI 0.43–0.64), indicating that AR expression in breast tumors was an indicator of low risk of recurrence." (PMID 24324816, 2013). "Finally, we linked the MCF‐7 breast tumor‐targeting peptide AR with the PEI on the ZS/ID‐P NPs (termed AR‐ZS/ID‐P NPs) to selectively inhibit the breast tumor." (PMID 37610511, 2023). "Moreover, an earlier study based on the same cohort found that MHT was associated with breast tumor androgen receptor (AR) positivity and AR positivity conferred better prognosis in AI-treated patients." (PMID 32117735, 2020). "Also, a very recent study demonstrated the association between the presence of AR+ CTCs and the formation of bone metastases in patients with ER+ breast tumors." (PMID 32012729, 2020). "The AR peptide facilitated selective accumulation of the nanoparticles in MCF‐7 breast tumors, utilizing the peptide's affinity for tumor‐specific markers." (PMID 40787898, 2025). "After loading DOX and ICG into the porous ZIF‐8 structure, the nanoparticles were coated with polyethylenimine for enhanced stability and surface modification with the breast tumor‐targeting peptide AREYGTRFSLIGGYR (AR peptide)." (PMID 40787898, 2025). "Androgen receptor (AR) expression is typically high in luminal breast tumors but varies by cancer types, being generally lower in basal subtypes." (PMID 40867349, 2025). "The current study aimed to assess the proliferative behavior of AR-positive breast tumors by correlating AR expression with the Ki67 labeling index." (PMID 39497884, 2024). "One of the targets that has been considered is the androgen receptor (AR), which is expressed in 70–90% of ER+ breast tumors." (PMID 39338407, 2024). "For example, psychological stress-activated β2 adrenergic receptor triggers AR-cyclic AMP (cAMP)-protein kinase A (PKA) signaling to accelerate breast tumor growth." (PMID 37845207, 2023). "The estrogen receptor has been found to interact with the androgen receptor, further enhancing the radiosensitivity of breast tumors." (PMID 38066611, 2023). "This is a therapeutic advantage, as AR acts as a breast tumor suppressor, a mechanism of action similar to the observed for the non-steroidal AI letrozole and to other C7- and C6-substituted steroidal AIs synthesized by our group." (PMID 36677847, 2023). "The expression of androgen receptor (AR) in BC is frequent and occurs in more than 70% of breast tumors." (PMID 37835528, 2023). "AR expression/action in breast tumors appears to be clinically relevant and disease-context-specific." (PMID 37686282, 2023). "Similar to breast tumors, salivary duct carcinomas stain positive for AR, which is detected in up to 98% of tumors." (PMID 37626712, 2023). "miR-135b, a direct regulator of AR in PC cells, was shown to have a lower expression in ER+ breast tumors when compared to ER−, as well as a higher expression in AR-low BC patient samples." (PMID 37626796, 2023). "Our results showed that AR + breast tumors were stiffer, which indicates that a higher degree of fibrosis and a relatively lower proportion of cancer cells in the AR + group lead to the slow progression of cancer." (PMID 36929229, 2023).
breast tumors (continued). "Accordingly, we found a positive correlation between FOXA1 and AR expression in breast tumors, while transient silencing of FOXA1 led to decreased AR mRNA expression levels in SNAI1-KO cells." (PMID 36171192, 2022). "Molecular studies have identified breast tumours with apocrine features and high expression of androgen receptor mRNA including ‘luminal androgen receptor tumours’ and ‘molecular apocrine tumours’." (PMID 34537861, 2022). "AR is poised to be a promising therapeutic target for breast tumors, and numerous anti-androgen drugs are in the development pipeline; however, the role of AR as a predictive biomarker in clinical practice is uncertain." (PMID 35884530, 2022). "The results from these trials will continue to shed light on the use of antagonists and agonists for the treatment of AR+ and/or ER+ breast tumours." (PMID 35618789, 2022). "AR + /ER + /PR + breast tumors were smaller, had decreased Ki67, and patients had better survival compared to their AR + /ER − /PR − counterparts." (PMID 35761157, 2022). "Women with breast tumors with higher expression of AR are in general known to have better survival outcomes while a high AR/ER ratio is associated with poor outcomes in hormone receptor positive breast cancers mostly in post menopausal women." (PMID 34234742, 2021). "In a study, ER- breast tumors exhibited cross-talk between AR and HER2, resulting in their proliferation." (PMID 34638264, 2021). "A majority (~70%) of breast tumors express estrogen receptor (ER), and a significant fraction (~90%) of these ER-positive (ER+) breast tumors is also androgen receptor-positive (AR+)." (PMID 34136389, 2021). "But the androgen receptor (AR) is also found to be expressed in the majority of breast tumor tissues, and AR is known to participate in the pathology and development of BRCA." (PMID 33805346, 2021). "In turn, GRα is repressed by Akt1, which phosphorylates its S134 residue GRβ is preferentially expressed with AR in breast tumors and was revealed to be present in 92.1% of specimens, typically in triple-negative tumors." (PMID 34638264, 2021). "According to the results of tissue microarrays from 3093 patients, 77% invasive breast carcinomas are androgen receptor (AR) positive, indicating AR is frequently expressed in breast tumors." (PMID 34575114, 2021). "Enzalutamide has been shown to be effective in AR+ breast tumors, including ER+ (MCF-7) cells and ER− (MDA-MB-453) cells." (PMID 33062889, 2020). "Only few studies have been conducted in Africa to characterize Androgen receptor (AR) in breast tumor." (PMID 32374753, 2020). "This ligand-driven transcription factor is widely expressed in primary and metastatic breast tumors and specifically, 75% of HR+ BCa tissue samples express AR." (PMID 32948192, 2020). "As discussed, AR can trigger or suppress the oncogenic features of breast tumors depending on the bioavailability of estrogens." (PMID 31952272, 2020). "The androgen receptor (AR) is expressed in 60–80% of breast tumors, though its prevalence is correlated with tumor ER expression." (PMID 30795773, 2019). "Various GES indicated that C1 clustered molecular apocrine (luminal androgen receptor) breast tumors." (PMID 31101122, 2019). "KDM4A and KDM4B are considered promising therapeutic targets for prostate and breast tumor growth based on their functions as coactivators of androgen receptor and estrogen receptor, respectively." (PMID 30683841, 2019). "On the other hand, Santagata and colleagues compared 3,157 human breast tumors to normal cell types and divided them into four major subtypes that were differentiated by ER, androgen receptor (AR), and vitamin D receptor (VDR) status." (PMID 29707142, 2018). "In the primary breast tumor and corresponding metastatic breast tumor of the same donor (a 65-year-old female, BioChain, Hayward, CA, USA), the expression levels of AR and KCa1.1 transcripts were higher in metastatic tissue than in the primary tumor." (PMID 29713287, 2018).
breast tumors (continued). "Our data reveal that genomic functions of ERα and AR in male breast tumors are largely overlapping, which strongly co-localized with GR and PR at the same regions." (PMID 29396493, 2018). "Practically all AR sites were co-occupied with ERα, which was also seen in female breast tumor and MCF7 cells." (PMID 29396493, 2018). "Enzalutamide, a more potent AR inhibitor, achieved single-agent activity in 20–40% of advanced TN breast tumors expressing AR." (PMID 29382369, 2018). "Bicalutamide reached a 19% clinical benefit rate in a phase 2 trial in ER-/PR- breast tumors expressing AR." (PMID 29382369, 2018). "Observed changes in PSA and PGR expression in prostate and breast tumors as markers of AR and ERα signaling, respectively, reflected the natural tumor heterogeneity observed clinically for each tumor type examined." (PMID 30117261, 2018). "Whereas 70%–90% of all breast tumors are AR+ and AR overexpression is correlated with endocrine resistance, but the precise molecular mechanism(s) for this association is yet to be studied." (PMID 29254284, 2017). "So it's essential to further study by a combined approach of microarray, RNA-seq, ChIP-seq, and ATAC-seq to determine which sets of genes regulated by AR in ER+ breast tumors." (PMID 29254284, 2017). "In contrast, molecular apocrine breast tumors are characterized by apocrine histopathological features, ER-negativity, AR-positivity, and HER2 amplification." (PMID 29137314, 2017). "In this review, we discussed the complex AR signaling pathway in ER+ breast tumor under the condition of hormonal levels of post-menopausal women." (PMID 29254284, 2017). "We began by interrogating the expression of AR in >2000 human breast tumor samples at both the RNA and protein level using the TCGA data set." (PMID 28840192, 2017). "A majority (~70%) of breast tumors are found to express estrogen receptor, and a significant portion (~90%) of ER-positive (ER+) breast tumors are also androgen receptor-positive (AR+)." (PMID 29254284, 2017). "Clearly, AR and ER status of a breast tumor will determine the effect of an (anti)androgen on breast tumor cell proliferation." (PMID 29083379, 2016). "Our findings suggest that there are a significant number of ER−/Her2+ breast tumors express Lin28A and AR and Lin28A can activate AR expression." (PMID 27494865, 2016). "In this study, we found that Lin28A can activates androgen receptor(AR) via regulation of c-myc and promote ER-/Her2+ breast tumor growth." (PMID 27494865, 2016). "A more recent study demonstrated that the AR/ER ratio influences breast tumor responses to hormonal treatment." (PMID 29083379, 2016). "Collectively, these data and the widespread expression of AR in primary and metastatic breast tumours, justify a careful examination of the therapeutic potential of androgens also in potentiating the effectiveness of anti-oestrogen adjuvant therapies." (PMID 26862856, 2016). "Nevertheless, more recent results, including those from our study, again indicate a possible role of the AR in inhibiting breast tumor progression." (PMID 29083379, 2016). "We initially determined Lin28A and AR expression in ER-/Her2+ and ER-/Her2- breast tumor cells lines." (PMID 27494865, 2016). "Collectively, our data and the widespread AR expression in primary and metastatic breast tumours, suggest a careful examination of the therapeutic potential of androgens also in potentiating the effectiveness of anti-oestrogen adjuvant therapies." (PMID 26862856, 2016). "Herein, we show that in addition to the prototypical transcript, the AR gene produces a diverse range of AR-V transcripts in primary breast tumors." (PMID 26554309, 2015). "Our in vitro and preclinical results demonstrate that enzalutamide inhibits androgen-stimulated growth of both ER+/AR + and ER–/AR + breast tumors." (PMID 24451109, 2014).
breast tumors (continued). "If the presence of androgen synthesising pathways can play a role on AR expression in breast tumour cells is therefore a big controversial in several study." (PMID 23816265, 2013). "We propose here, in ER(-) breast tumors, a composite signature including AR gene expression pathway analysis by qRT-PCR in addition to "HER2(3+) or GCDFP15(+)" protein expression by IHC." (PMID 23663520, 2013). "The pioneer factor FOXA1 also plays an important role in androgen receptor (AR) signaling of molecular apocrine tumors, which have been recently identified as an additional subgroup of ER-negative and AR-positive breast tumors." (PMID 23192763, 2013). "Meta-analysis showed that AR expression in breast tumors was an indicator of better DFS (HR 0.52, 95% CI 0.43-0.64)." (PMID 24324816, 2013). "Third, clinical data indicate that expression of AR occurs more frequently than ER in breast tumor tissue." (PMID 24324894, 2013). "We found that PIP is the most regulated molecular apocrine gene by the AR-ERK feedback loop and is overexpressed in ER-/AR+ breast tumors." (PMID 22817771, 2012). "We next examined PIP protein expression using IHC in a cohort of twenty-four ER- breast tumors with known AR expression status." (PMID 22817771, 2012). "ER- breast tumors were classified into AR+ and AR- subgroups as described in the Methods section and a total of twelve samples (50% of tumors) showed AR+ staining in this cohort." (PMID 22817771, 2012). "The levels of Androgen receptor protein in a cohort of breast tumour samples was determined by immunohistochemistry and the results were compared with clinical characteristics, including survival." (PMID 22471922, 2012). "AR+ breast tumors showed a markedly higher expression of PIP (57% ± 6) compared to AR- tumors (16% ± 4), (P <0.01)." (PMID 22817771, 2012). "It is notable that AR expression is present in 40% to 50% of ER- breast tumors and the majority of these cases also have ErbB2 overexpression." (PMID 22817771, 2012). "It is known that at least 50% of ER-/AR+ breast tumors have ErbB2 overexpression, and anti-ErbB2 treatment is an established part of management for this subgroup." (PMID 21457548, 2011). "Positive immunoreactivity for both PSA and GCDFP-15 in breast tumours was highly dependent on AR status (odds ratios of 24.0 and 4.5 respectively), but unrelated to age, ER and PR status and axillary lymph node involvement." (PMID 9703283, 1998). "AR immunoreactivity was present in the nuclei of breast tumour cells and was correlated with oestrogen receptor (ER; P < 0.05) and progesterone receptor (PR; P < 0.01) status." (PMID 9703283, 1998). "Notably, CLDN8 expression appears to positively correlate with androgen receptor (AR) status in breast tumors, and patients with concomitantly low CLDN8 and low AR expression have particularly unfavorable prognoses." (PMID 40508219, 2025). "In most patients, AR expression in breast tumours and BrM was comparable." (PMID 37345085, 2023). "Thus, considering the importance of AR in this type of breast tumor and the dual role of AR function after AI therapy, it is important to understand the involvement and the role of AR on Oxy action." (PMID 36677847, 2023). "AR status was concordant between the majority of BrM and matched primary breast tumours." (PMID 37345085, 2023). "Hence, in this study, we aimed to further clarify and analyze the specific signal transduction pathway(s) by which androgens/AR exert their protective, anti-proliferative/pro-apoptotic effect in ER+ breast tumors." (PMID 37686282, 2023). "A subsequent study examined AR-SV expression in primary breast tumors." (PMID 37626712, 2023). "AR is the androgen receptor gene and is expressed in the majority of primary breast tumors." (PMID 35428183, 2022). "Additionally, NFATc4 is highly co-expressed with androgen receptor (AR) which is expressed in 88% ER-positive breast tumors." (PMID 35698138, 2022).